ADA2 (adenosine deaminase 2)
Diseases named in the same sentence as ADA2 in open-access papers (continued):
Sharing a sentence is not in itself a finding about the gene and the disease.
polyarteritis nodosa (30 papers, 2014 to 2025). Polyarteritis nodosa (PAN) is a rare, clinically heterogeneous, rheumatologic disease characterized by necrotizing inflammatory lesions affecting small- and medium-sized blood vessels. "Deficiency of Adenosine Deaminase 2 (DADA2) is a heterogenous disorder due to biallelic mutations in ADA2 that typically presents in childhood with a vasculopathy similar to polyarteritis nodosa." (PMID 38758417, 2024). "Vasculopathy, associated with hemorrhagic and ischemic strokes in ADA2 deficiency, has an early-onset as well as clinical and histopathological characteristics of polyarteritis nodosa (PAN)." (PMID 35163523, 2022). "ADA2 deficiency was first described in two major articles, one in patients with fever, visceral and cutaneous lesions compatible with polyarteritis nodosa, and the other in patients with peripheral and central nervous system involvement." (PMID 35261770, 2022). "Here we present three instructive scenarios of ADA2 deficiency that represent the typical clinical patterns: recurrent ischemic strokes (Patient 1), polyarteritis nodosa (Patient 2) and pure red cell aplasia (Patient 3)." (PMID 35774100, 2022). "ADA-2 deficiency is characterized by early-onset vasculopathy with the clinical and histopathological features of polyarteritis nodosa (PAN), associated with hemorrhagic and ischemic strokes." (PMID 34133513, 2021). "Lastly, CECR1, which could only be analyzed with SKAT, encodes an adenosine deaminase (ADA2) and has been associated with Cat Eye Syndrome, Sneddon’s syndrome and Polyarteritis nodosa." (PMID 28814775, 2017). "Of note, a childhood onset of vasculopathy overlapping polyarteritis nodosa caused by a single gene defect in CECR1 (Cat Eye Syndrome Chromosome Region Candidate 1) resulting in deficiency of adenosine deaminase 2 has also been reported in families with autosomal recessive inheritance pattern." (PMID 27018080, 2016). "Patients with ADA2 deficiency classically present with early onset polyarteritis nodosa (PAN) in addition to hemorrhagic and ischemic stroke." (PMID 32737687, 2020). "Deficiency of adenosine deaminase 2 (DADA2) is a recently described monogenic autoinflammatory disease that can mimic polyarteritis nodosa (PAN)." (PMID 29963054, 2018). "Deficiency of adenosine deaminase 2 (ADA2) is a rare systemic vascular inflammatory disorder, also known as polyarteritis nodosa with childhood-onset (PAN; OMIM 615688)." (PMID 28830446, 2017). "The deficiency of Adenosine Deaminase 2 (DADA2) is a recently identified disease, gathered in the family of autoinflammatory diseases, mainly characterised by early-onset polyarteritis, hemorrhagic and ischemic strokes and hypogammaglobulinemia." (PMID 27609179, 2016). "Deficiency of adenosine deaminase 2 (DADA2) is a complex monogenic autoinflammatory disease first described in 2014 by two separate groups as a syndrome of recurrent fever, livedo racemosa, early-onset strokes, and peripheral vasculopathy resembling polyarteritis nodosa (PAN)." (PMID 38357265, 2023). "The deficiency of adenosine deaminase 2 (DADA2) is an autosomal recessively inherited disease that has undergone extensive phenotypic expansion since being first described in patients with fevers, recurrent strokes, livedo racemosa, and polyarteritis nodosa in 2014." (PMID 35095905, 2021). "Adenosine deaminase 2 deficiency (DADA2) was first described in 2014 in patients with a small- and medium-vessel vasculitis resembling polyarteritis nodosa (PAN)." (PMID 34198614, 2021).
Stroke (18 papers, 2016 to 2024). Sudden impairment of blood flow to a part of the brain due to occlusion or rupture of an artery to the brain. "The majority of the reported strokes caused by ADA2 deficiency are ischemic, while many hemorrhagic strokes were also described." (PMID 39161369, 2024). "ADA2 deficiency is a rare stroke etiology, but should be suspected especially in young stroke patients with lab abnormalities suggesting CVID." (PMID 37306896, 2023). "We report here the case of a 13-year-old Caucasian girl with a novel frameshift variant in the ADA2 gene and a clinical phenotype of early-onset stroke." (PMID 36528591, 2022). "Nevertheless, specific signs such as early onset stroke, parental consanguinity, or a familial history of the condition, along with a lack of response to standard treatments, should prompt consideration for ADA2 deficiency." (PMID 39239002, 2024). "However, ADA2 deficiency was associated with a spectrum of vascular and inflammatory phenotypes, including early-onset recurrent stroke and systemic vasculopathy." (PMID 35663977, 2022). "Screening for ADA2 pathogenic variants should be considered in the differential diagnosis of pediatric patients manifesting with chronic thrombocytopenia or early-onset stroke for an accurate diagnosis and appropriate treatment choices." (PMID 34221752, 2021). "Human adenosine deaminase type 2 (ADA2) deficiency (DADA2) is a recently described inherited autoinflammatory inborn error of immunity (IEI), characterized by systemic vasculitis with stroke, cytopenia and bone marrow failure and immunodeficiency." (PMID 38970744, 2024). "Therefore, stroke, encephalitis, posterior reversible encephalopathy, mononeuropathy and polyneuropathy, and Behçet’s disease-like presentations should prompt healthcare professionals to consider excluding ADA2 deficiency, especially, but not only in childhood." (PMID 38970744, 2024). "In 2014, a compound heterozygous mutation in the adenosine deaminase 2 (ADA2) gene was identified in a large Portuguese family, who presented with livedo reticularis, stroke during early adulthood, leg ulcerations and intermittent fever." (PMID 32980981, 2021). "Unlike in ADA2 deficiency, where stroke is predominant, in our cohort of 8 patients, only one patient had a stroke." (PMID 33193364, 2020). "Therefore, stroke, encephalitis (including ADEM), PRES, mononeuropathy and polyneuropathy, and Behçet’s disease-like presentations should prompt the neurologist to exclude ADA2 deficiency, especially but not only in childhood." (PMID 37548813, 2023). "Cognitive features were the most common clinical cerebral phenotype for 4 of 7 genes (HTRA1HomZ, COL4A2, HTRA1HetZ, and CTSA); stroke was the most common among individuals with COL4A1 and ADA2, and headache was most common among individuals with TREX1." (PMID 35699195, 2022). "Clinical phenotype frequencies varied widely: stroke, 9% (TREX1) to 52% (HTRA1 heterozygotes); cognitive features, 0% (ADA2) to 64% (HTRA1 homozygotes); and psychiatric features, 0% (COL4A2; ADA2) to 57% (CTSA)." (PMID 35699195, 2022). "The frequency of clinical stroke ranged from 22% to 52% for 6 of 7 genes (COL4A2, 22% [9/41]; HTRA1HomZ, 30% [13/44]; ADA2, 33% [115/346]; COL4A1, 41% [161/390]; CTSA, 50% [7/14]; HTRA1HetZ, 52% [43/82]), while only 9% (11/123) of TREX1 individuals were reported to have suffered a clinical stroke." (PMID 35699195, 2022).
bone marrow failure (13 papers, 2018 to 2026). "Minimal residual activity of ADA2 enzyme was thought to be associated with pure red cell aplasia and bone marrow failure." (PMID 33757531, 2021). "We describe a case of a young woman with a long history of ALPS during childhood followed by rapid evolution to bone marrow failure, which resulted from carrying a novel pathogenic genotype of the ADA2/CECR1 gene." (PMID 34721429, 2021). "Specific clinical features, such as pure red cell aplasia and bone marrow failure, were reported to correlate with the lower level of ADA2 enzyme activity." (PMID 33757531, 2021). "Although HLH has been reported in patients with adenosine deaminase 2 (ADA2) deficiency, to date it has not been reported in individuals harboring pathogenic variants in ERCC6L2, a gene typically linked to inherited bone marrow failure." (PMID 41710027, 2026).
cat-eye syndrome (13 papers, 2014 to 2025). Cat eye syndrome (CES) is a rare chromosomal disorder with a highly variable clinical presentation. "The deficiency of adenosine deaminase 2 (DADA2) is related to a mutation in the CECR1 gene (cat eye syndrome chromosome region, candidate 1) encoding for the ADA2 protein, which is mainly present in myeloid cells as a secreted protein." (PMID 34073717, 2021). "The underlying cause of DADA2 is biallelic (homozygous or compound heterozygous) loss of function mutations in adenosine deaminase type 2 (ADA2), formerly known as Cat Eye Syndrome Chromosome Region 1 (CECR1)." (PMID 37548813, 2023). "Adenosine Deaminase 2 (ADA2; also known as cat eye syndrome chromosome region, candidate 1 gene; CECR1) exon sequencing and serum ADA2 levels were performed to confirm the diagnosis of DADA2." (PMID 29963054, 2018). "For PAN patients with early-onset, familial history or poor treatment response, testing for the cat eye syndrome chromosome candidate gene 1 and assessing ADA2 enzyme activity can assist in the diagnosis of DADA2 and facilitate timely treatment with tumor necrosis factor inhibitors." (PMID 39183419, 2024). "Adenosine Deaminase 2 Deficiency (DADA2) (OMIM: 607575) is a monogenic, autoinflammatory disease caused by the loss of functional homozygous or heterozygous mutations in the ADA 2 gene (previously CECR1, Cat Eye Syndrome Chromosome Region 1)." (PMID 34577178, 2021). "The Deficiency of Adenosine Deaminase 2 (DADA2) (OMIM: 607575) is a monogenic, autoinflammatory disease caused by the loss of functional homozygous or heterozygous mutations in the ADA 2 gene (previously CECR1 Cat Eye Syndrome Chromosome Region 1)." (PMID 34577178, 2021).
tuberculosis (10 papers, 2014 to 2025). A chronic, recurrent infection caused by the bacterium Mycobacterium tuberculosis. "Previous studies have shown a positive correlation between ADA2 activity and myeloid-cell-mediated diseases such as tuberculosis and macrophage activation syndrome." (PMID 40332245, 2025). "It has been shown that ADA2 activity increases in the pleural fluid of patients with tuberculosis (TB)." (PMID 40895545, 2025). "Previous studies found that ADA2 levels increased in some diseases, such as rheumatoid arthritis, tuberculosis, T cell lymphoblastic malignant tumor, autoimmune liver disease, and acquired immunodeficiency syndrome (AIDS)." (PMID 36124285, 2022). "Meanwhile, the ratio of ADA2 to the total ADA (mean: 90.63%) increased significantly in the tuberculosis group, indicating the increased pleural ADA2 accounts for the high activity of ADA in the effusion fluid." (PMID 24984978, 2014). "In this study, patients in the low ADA group had a high proportion of ADA2 activity, similar to that of patients in the high ADA group, which implies a similar effect of tuberculosis-related immune reactions." (PMID 31937286, 2020). "Additionally, our findings suggest that the test could be adapted to detect pleural tuberculosis, as pleural fluid ADA2 levels are significantly elevated in TB patients compared to non-TB individuals." (PMID 40936927, 2025). "Our study introduces a novel rapid antigen test (RAT) for detecting adenosine deaminase 2 (ADA2) in saliva and pleural fluid, providing a convenient and noninvasive method for the preliminary diagnosis of DADA2 and potentially pleural tuberculosis (TB)." (PMID 40936927, 2025).
neutropenia (9 papers, 2018 to 2026). A decrease in the number of neutrophils found in the blood. "We report the fatal case of a female patient with a novel mutation for ADA2 deficiency who displayed isolated severe neutropenia for over 6 years before additional symptoms." (PMID 37647436, 2023). "Four patients had underlying non-malignant hematological conditions, two with aplastic anemia, one with beta-thalassemia following SCT, and one with neutropenia due to adenosine deaminase deficiency type 2 (ADA2)." (PMID 35448618, 2022). "We report a case with atypical clinical presentation of perianal abscess in the setting of leukopenia and neutropenia at disease onset in which whole‐exome sequencing revealed a homozygous pathogenic variant c.882‐2A>G in ADA2 gene suggesting VAIHS." (PMID 35261770, 2022). "Knockdown of ADA2 in the Zebrafish model was shown to cause neutropenia, supporting an intrinsic role of ADA2 in normal hematopoiesis." (PMID 30406060, 2018). "This study reveals that cecr1b deficiency in zebrafish accurately mirrors human DADA2 traits, including neutropenia, vascular dysfunction, and inflammation, underscoring the functional similarity between ADA2 and Cecr1b." (PMID 38777862, 2024). "An ADA2 knocked-down zebrafish model displays neutropenia, thus supporting an intrinsic role of ADA2 in normal hematopoiesis." (PMID 34721429, 2021). "CECR1 mutations, which cause deficiency of adenosine deaminase 2 (DADA2), are associated with cytopenias—including AIHA, thrombocytopenia, and severe neutropenia—that may occasionally be the initial clinical presentation." (PMID 40993545, 2025). "A challenging case of VAIHS with atypical presentation and ADA2 mutation highlights the consideration of ADA2 deficiency as a differential diagnosis of enlarging cutaneous abscess with no wound healing in the setting of leukopenia and neutropenia." (PMID 35261770, 2022). "The LoF of cecr1b, but not cecr1a, leads to neutropenia and intracranial hemorrhages, successfully corrected by overexpressing human ADA2 mRNA1." (PMID 38777862, 2024).
glioma (8 papers, 2018 to 2023). A benign or malignant brain and spinal cord tumor that arises from glial cells (astrocytes, oligodendrocytes, ependymal cells). "CECR1 has been linked to macrophage polarization to immunosuppressive M2 phenotype in glioma and triple-negative breast cancer (TNBC), and ADA2 inhibition in a mouse model of TNBC led to decreased tumor growth in vivo and decreased invasion in vitro." (PMID 35205651, 2022).
ischemic stroke (8 papers, 2020 to 2025). A stroke disorder caused by obstruction of blood flow to the brain, due to thrombotic (local blood clot formation) or embolic (due to a blood clot or other material traveling from another site) event. "DADA2, FMF and CAPS were associated with ischemic stroke, whereas hemorrhagic stroke was only present in ADA2 mutations." (PMID 38632524, 2024). "Treatment of ADA2 deficiency involves anti-tumor necrosis factor alpha agents, which prevent and eliminate manifestations of autoinflammatory disease, reduce the risk of ischemic stroke, and relieve immunodeficiency." (PMID 41362886, 2025). "Consequently, ADA2 deficiency should be considered despite normal inflammatory markers and/or evidence of cerebral vasculitis and ADA2 mutation screening should be conducted in children with otherwise unexplained ischemic stroke." (PMID 38357265, 2023). "Deficiency of adenosine deaminase 2 (DADA2) was first described in 2014 in 9 patients with intermittent fever, systemic vasculopathy early-onset ischemic stroke, caused by recessive mutations in CECR1 encoding ADA2." (PMID 34867986, 2021). "Some authors recommend treatment initiation when biallelic ADA2 variants coincide with the absence of catalytic ADA2 activity in both symptomatic and asymptomatic patients, to reduce the risk of ischemic stroke and prevent severe neurological complications." (PMID 35774100, 2022).
Pleural effusion (8 papers, 2018 to 2025). The presence of an excessive amount of fluid in the pleural cavity. "Our meta-analysis extracted and pooled the data from 13 eligible studies, and the results suggested that pleural ADA2 played a role in differentiating TPE from other types of pleural effusion." (PMID 36124285, 2022). "Mononuclear cells in 23 human pleural effusion samples were investigated for total IL-32, IL-32 isoforms (IL-32α, IL-32β, and IL-32γ), and ADA2 mRNA expression, and correlation studies were performed." (PMID 35880892, 2022). "Myeloid cells are known to release ADA2 during inflammatory responses, and high levels of ADA2 are found in plasma samples and pleural effusions of patients with infectious diseases or chronic inflammation." (PMID 29951947, 2018). "Thus, ADA2 has been suggested for the diagnosis of TB pleural effusion." (PMID 40895545, 2025). "To validate the ADA2 ELISA with anti-ADA2 scFv-AP, we analyzed pleural effusions from 41 patients with pleural TB and 47 with non-TB effusions." (PMID 40895545, 2025). "Our results showed that ADA2 levels in pleural effusions from patients are significantly higher than those in non-TB exudates." (PMID 40895545, 2025). "However, due to non-standardized and costly ADA2 assays, total ADA levels in pleural effusion remain the primary marker in the clinical setting.The currently accepted ADA cut-off value is 40 U/L, but the threshold value ranges from 17.5 to 77 U/L among different studies and decrease with age." (PMID 38750432, 2024).
severe combined immunodeficiency (8 papers, 2016 to 2026). Severe combined immunodeficiency (SCID) comprises a group of rare monogenic primary immunodeficiency disorders characterized by a lack of functional peripheral T lymphocytes resulting in early-onset severe respiratory infections and failure to thrive. "Adenosine deaminase 2 (ADA2) was first described as the residual source of adenosine deaminase activity in the spleen of a patient with severe combined immunodeficiency (SCID) due to adenosine deaminase deficiency (ADA; also known as ADA1)." (PMID 29951947, 2018). "The literature includes several case reports of children presenting with prolonged fever who were later diagnosed with various PIDs, such as deficiency of adenosine deaminase 2, severe combined immunodeficiency, Wiskott-Aldrich syndrome, and Schimke immunoosseous dysplasia." (PMID 41300611, 2025). "The two major ADA isoforms are ADA1, whose deficiency is cause of a severe combined immunodeficiency (SCID), and ADA2." (PMID 27609179, 2016). "The genetic deficiency of ADA1 results in severe combined immunodeficiency (SCID), while lack in ADA2 (DADA2) results in multiple phenotypes ranging from systemic inflammation to vascular pathology." (PMID 35967411, 2022).